NPC1 (NPC intracellular cholesterol transporter 1)
Diseases named in the same sentence as NPC1 in open-access papers (continued):
Sharing a sentence is not in itself a finding about the gene and the disease.
lysosomal storage disorder (continued). "NPC is a lysosomal storage disorder caused by the pathogenic deficiency of either the NPC1 or NPC2 gene." (PMID 30023294, 2018). "TMEM97 is thought to be involved in cholesterol trafficking through its association with lysosomal cholesterol transporter NPC1, a protein whose loss results in a fatal lysosomal storage disorder, Niemann–Pick disease type C119." (PMID 30443021, 2018). "NPC disease is a progressive neurodegenerative lysosomal storage disease caused by mutations in either the NPC1 or NPC2 genes." (PMID 29119141, 2017). "Niemann-Pick Type C1 (NPC1) is an autosomal recessive lysosomal storage disease caused by mutations in the NPC1 gene located on chromosomal band 18q11." (PMID 27834854, 2016). "Niemann-Pick type C (NPC) disease is a neurodegenerative lysosomal storage disease caused by mutations in either the NPC1 or NPC2 gene." (PMID 27019000, 2016). "Niemann Pick C [NPC-MIM 257220; MIM607625] disease is a neurodegenerative lysosomal storage disorder due to mutations in NPC1 or NPC2 genes." (PMID 25396745, 2014). "Niemann-Pick C disease (NPC) is an autosomal recessive lysosomal storage disorder characterized by accumulation of unesterified cholesterol and other lipids within the lysosomes due to mutation in NPC1 or NPC2 genes." (PMID 25396745, 2014). "Niemann Pick C (NPC) disease is a neurovisceral lysosomal storage disorder due to mutations in NPC1 or NPC2 genes, characterized by the accumulation of endocytosed unesterified cholesterol, gangliosides and other lipids within the lysosomes/late endosomes." (PMID 23433359, 2013). "Niemann-Pick Type C (NPC) is a neurodegenerative, lysosomal disorder caused by defects in function of either genes Npc1 or Npc2, although in 95% of patients disease is caused by defect in Npc1." (PMID 23094108, 2012). "This notion is best illustrated by the severe progressive neurodegeneration in Niemann-Pick Type C (NPC) disease, one of the lysosomal storage diseases, caused by mutations in the NPC1 or NPC2 gene." (PMID 20386595, 2010). "This inherited lysosomal disorder is caused by loss-of-function mutations in the NPC1 gene." (PMID 39207850, 2024). "At variance with the paucity of zebrafish models for the aSMase-deficient forms of NPD, various attempts have been made to model the type C form of NPD, a lysosomal storage disease distinct from sphingolipidoses that depends on cholesterol trafficking defects due to mutations in NPC1 or NPC2 genes." (PMID 36902174, 2023). "Mutations in acid sphingomyelinase (aSMase), encoded by SMPD1, are causative of the NPD type A and B forms, whereas NPD type C, a lysosomal storage disease distinct from sphingolipidoses, is a cholesterol trafficking defect due to mutations in NPC1 or NPC2 genes." (PMID 36902174, 2023). "Interestingly, the lysosomal storage disorder Niemann Pick’s disease is caused by a mutation in the cholesterol-transporting proteins NPC1 or NPC2, which results in the accumulation of cholesterol in lysosomes." (PMID 32365555, 2020). "While mutations in the gene encoding for the lysosomal membrane protein Niemann-Pick type C1 (NPC1) are well-known to induce a rare lysosomal storage disease, recent findings have also linked a dysfunctional NPC1 protein to the development of obesity and MetS5,6." (PMID 31628414, 2019). "To determine whether PGRN deficiency results in similar transcriptional changes as seen in other mouse models of lysosomal storage diseases, we used a publicly available microarray dataset of brain mRNAs isolated from Npc1-deficient (Npc1−/− mice." (PMID 28903038, 2017). "Niemann-Pick type C1 (NPC1) disease is an inherited lysosomal storage disease caused by mutation of the Npc1 gene, resulting in a progressive accumulation of unesterified cholesterol and glycolipids in lysosomes of multiple tissues and leading to neurodegeneration and other disease." (PMID 25472750, 2014).
lysosomal storage disorder (continued). "We next investigated whether a MSR arose in response to the I1061T variant of the NPC1 protein responsible for the lysosomal storage disease Niemann-Pick type C1, which, like CF, is characterized by protein misfolding and ERAD-mediated clearance." (PMID 25406061, 2014). "Moreover, the cells provide the opportunity to analyze the consequences of a NPC1 mutation on the patient-specific (epi)genetic background, and will thus serve to elucidate further the pathogenic mechanisms of this fatal lysosomal storage disorder." (PMID 24044630, 2013). "In addition, the 1H NMR metabolic profile of plasma from corresponding heterozygous carriers was found to be distinct from those of both healthy controls and NPC1 patients, and this provides novel insights into the underlying mechanisms of this rare lysosomal storage disease." (PMID 28740230, 2017). "NPC1 loss of function is the major cause of NPC disease, a rare lysosomal storage disorder characterized by an abnormal accumulation of lipids in the late endosomal/lysosomal network, mitochondrial dysfunction, and impaired autophagy." (PMID 37047194, 2023). "Niemann-Pick type C (NPC) disease is a lysosomal storage disease (LSD) characterized by the buildup of endo-lysosomal cholesterol and glycosphingolipids due to loss of function mutations in the NPC1 and NPC2 genes." (PMID 37567876, 2023). "To stablish the unique nature, or otherwise, of the inflammasome signature in Krabbe disease, we performed comparative studies with mouse models of the lysosomal storage diseases Sandhoff and NPC1." (PMID 36519759, 2023). "Defective autophagy is implicated in the pathogenesis of many neurodegenerative and lysosomal storage diseases including NPC1, where impaired autophagosome–lysosome (AP-LY) fusion has been reported." (PMID 34023384, 2021). "NPC1, a rare hereditary neurodegenerative disease, belongs to the family of lysosomal storage disorders." (PMID 33081384, 2020). "Mutations in NPC1 and NPC2 cause Niemann Pick type C, a lethal lysosomal storage disease characterised by lysosomal cholesterol accumulation in multiple organ systems." (PMID 33144569, 2020). "Niemann–Pick type C1 (NPC1) is a lysosomal storage disorder, inherited as an autosomal-recessive trait." (PMID 32599915, 2020). "In this study, we have found that Tangier disease shares several cellular characteristics with those of the lysosomal storage disorder NPC1." (PMID 31707734, 2020). "Twenty-four new mutations were identified in NPC1, one in NPC2 and three in SMPD1, confirming the diagnostic potential of 3β,5α,6β-triol for the lysosomal storage diseases NPC and NPB." (PMID 29227331, 2018). "NPC1 is a fatal neurodegenerative lysosomal storage disorder characterized by abnormal accumulation of unesterified cholesterol and sphingolipids in late endosomes/lysosomes of many cell types." (PMID 25866316, 2015). "We investigated the possible role of rare sequence variants in the NPC1 and NPC2 genes, mutations in which are causative for the lysosomal storage disorder NPC, in three age-related neurodegenerative diseases (PD, FTLD, PSP)." (PMID 24386122, 2013). "In the genetic lysosomal storage disease Niemann-Pick C (NPC), caused by loss of NPC1 function, the expression of complement system components, C1q especially, is elevated in degenerating brain regions of Npc1-/- mice." (PMID 22985423, 2012). "However, for lysosomal storage diseases such as NPC1, such studies are hampered by the very limited availability of biofluid samples for their investigation." (PMID 37887404, 2023). "Genetic dysfunctionality of NPC1 may cause fatal NPC disease, a lysosomal storage disorder, due to the accumulation of cholesterol in lysosomes." (PMID 35631123, 2022). "In addition, mutations in the NPC intracellular cholesterol transporter 1 (NPC1) gene, which cause the lysosomal disorder Niemann-Pick type C, have been associated with PD." (PMID 33036336, 2020).
lysosomal storage disorder (continued). "Mutations in NPC1 and NPC2 cause the lethal Niemann Pick type C (NPC) lysosomal storage disease." (PMID 33144569, 2020). "Some clinical features, however, overlap between lysosomal storage disorders as NPC1 and Parkinson’s disease, suggesting that the two disorders may be pathogenically linked." (PMID 31178699, 2019). "In addition, some other heterocyclic sterol probes (FP-2, FP-6, FP-8 and FP-10) label NPC1 cells effectively within 6 h, hence they can be used for detection of lysosomal storage disorders." (PMID 30258093, 2018). "On the other hand, fast labelling of lysosomes by FP-7 may be an advantage for detecting lysosomal storage disorders, as we observed very intensive staining of NPC1 fibroblasts using this probe within 2 h." (PMID 30258093, 2018). "Niemann-Pick type C (NPC) disease is a progressive lysosomal storage disorder with an estimated incidence of 1:100,000–120,000 among newborns, caused by an autosomal recessive mutation in the NPC1 (95% of the cases; Online Mendelian Inheritance in Man no.: 257220) or NPC2 gene." (PMID 35007562, 2022). "It is noteworthy that the Nieman-Pick1 (NPC1) protein, which is involved in NPC disease (a fatal lysosomal storage disorder) and is also related to PTC, contains an intracellular PY motif and has highly dynamic trafficking." (PMID 26446620, 2015). "The restoration of cholesterol egress by MCS expansion when NPC1 is inhibited may offer potential for the development of novel therapeutics for NPC and other lysosomal storage diseases." (PMID 31537798, 2019). "We have previously demonstrated that a lysosomal storage disorder Niemann-Pick type C (NPC), in which free cholesterol accumulates in late endosomes/lysosomes due to NPC1/NPC2 dysfunction, shows cholesterol-dependent accumulation of intracellular Alzheimer's Aβ and APP-CTF fragments." (PMID 27902765, 2016).
Niemann-Pick disease, type C1 (59 papers, 2010 to 2026). "A missense mutation in NPC1 has also been identified in Niemann-Pick disease type D, a variant of NPC1." (PMID 32435656, 2020). "The lysosomal storage disease Niemann-Pick disease, type C1 (NPC1) is caused by a mutation of the NPC1 gene and results in a neurological disorder that is specifically related to the cerebellum." (PMID 26370973, 2015). "This term now encompasses the historical Niemann-Pick disease type D referring to the "Nova Scotia" isolate, later shown to be a genetic NPC1 variant." (PMID 20525256, 2010). "The first one, in French Acadians originating from Normandy and originally established in Nova Scotia, was initially described as Niemann-Pick disease type D; it is characterized by the NPC1 p.G992W mutation [1, 17, and 24]." (PMID 20525256, 2010). "For Niemann-Pick type C1 disease (NPC1), CyD was reported to overcome the transport defect in nearly every organ of NPC1 mice, leading to the excretion of sequestered cholesterol as bile acid." (PMID 31035393, 2019).
Niemann-Pick disease (41 papers, 2014 to 2025). A group of inherited, severe metabolic disorders in which sphingomyelin accumulates in lysosomes in cells. "One exception is the Patched homolog NPC1, which encodes a lysosomal cholesterol transporter associated with inherited metabolic disorder Niemann-Pick Disease." (PMID 40654857, 2025). "Niemann–Pick disease (NPC) is typically due to biallelic pathogenic variants in the NPC1 or NPC2 gene located on 18q11, with their encoded proteins having roles in the movement of lipids within cells." (PMID 38570878, 2024). "Patient #25 and patient #27 are patients diagnosed with “Niemann-Pick disease, type C1 / D,” carrying homozygous variants in the NPC1 gene." (PMID 38587696, 2024). "NPC1 is the pathogenic gene for Niemann-Pick disease, and patients with this disease often have concomitant sensorineural hearing loss." (PMID 38239289, 2023). "Niemann-Pick disease is an inherited neurodegenerative disorder, in which the NPC1 gene mutations result in abnormal cholesterol accumulation in lysosomes, associated with sensorineural hearing loss in some patients." (PMID 38239289, 2023). "A recent study from the International Niemann-Pick Disease Registry (INPDR) described 97 patients having NPC1 variants." (PMID 37433892, 2023). "NPC1 is a gene implicated in Niemann–Pick disease, an autosomal recessive lipid storage disorder characterized by progressive neurodegeneration caused by over-accumulation of cholesterol and glycosphingolipids in late endosomal/lysosomal compartments." (PMID 35207755, 2022). "One of the LSDs, Niemann–Pick disease, is caused by the loss of function of distinct lysosome-residing proteins, the acid sphingomyelinase and NPC1." (PMID 33946407, 2021). "In human Niemann–Pick disease, cholesterol and/or sphingolipids accumulate in late endosomes/lysosomes due to mutations in the intracellular cholesterol transport proteins NPC1 or NPC227, and is accompanied by an increase in Apolipoprotein D expression." (PMID 28904344, 2017). "In the top 5 quantiles of the green module, we found genes associated with spastic paraplegia (PLP1-OMIM#300401), Niemann-Pick disease (NPC1-OMIM#607623), and Canavan disease (ASPA-OMIM#271900)." (PMID 26707700, 2016). "However, a similar finding has been observed in Npc1−/− mice, a model of Niemann-Pick disease (NPC) type C, and which has been associated with Purkinje neuron loss." (PMID 36453132, 2022). "The hypothesis was built primarily on the basis of information on the comorbidity of Niemann–Pick disease caused by mutations in NPC1 and parkinsonism." (PMID 29867446, 2018). "The susceptibility of many disease genes (such as DMD, ATM, NPC1 (Niemann-Pick disease), F9 (hemophilia A), F8 (hemophilia B)) to aberrant pre-mRNA splicing has spawned creative therapeutic approaches that have been the focus of a great deal of time and effort." (PMID 24456648, 2014). "Npc1 (Niemann-Pick disease, type C1 intracellular cholesterol transporter 1) showed a cis eQTL co-aligned with a QTL for infusions, suggesting a possible link between Npc1 and this behavior." (PMID 39713377, 2025). "NPC1 and NPC2, the causative genes of Niemann–Pick disease, are responsible for the transport of free cholesterol in lysosomes." (PMID 38354786, 2024). "In order to identify candidate protein biomarkers for NPC1 we compared protein levels in cerebrospinal fluid (CSF) samples from individuals with Niemann-Pick disease, type C1 and non-NPC1 controls using a multiplexed proximal extension assay." (PMID 36721240, 2023). "The apolipoprotein E protein is associated with Alzheimer (M104310+) and heart disease (M617347), the NPC1 cholesterol trafficking regulator responsible for CNS lipid accumulation in Niemann–Pick disease (M257250)." (PMID 37504295, 2023). "Loss-of-function mutations in the intracellular cholesterol transporting protein NPC1 leads to Niemann-Pick disease, a severe form of early-onset neurodegeneration that features tau pathology." (PMID 35508140, 2022).
Niemann-Pick disease (continued). "The effects of NPC1 on lysosomal metabolism and mTOR signaling implicates autophagy in this model, and autophagy defects have been noted in Niemann–Pick disease models." (PMID 35884604, 2022). "As only 5% of patients suffering from Niemann-Pick disease harbor a mutation in NPC2 and 95% harbor a mutation in NPC1, the knowledge regarding the pathophysiology of NP-C1 is much more extensive than that regarding NP-C2." (PMID 33924575, 2021). "Bovine homologs for the genes that cause Niemann-Pick disease in humans (SMPD1, NPC1 and NPC2), are located on BTA15, BTA24 and BTA10 respectively." (PMID 32970694, 2020). "The primary pathogenesis of Niemann-Pick Disease (NPC) involves the disruption of lipid transport within cells, which is caused by mutations in either the NPC1 or NPC2 genes, with approximately 95% of cases associated with NPC1." (PMID 40106490, 2025). "Niemann-Pick disease is another neurodegenerative LSD, caused by mutations in NPC1." (PMID 38295116, 2024). "It is relevant to note that, during neuronal aging, the activation of the AKT-mTOR pathway triggers the degradation of NPC1 protein, which induces the accumulation of cholesterol in endosomal compartments, similarly to what occurs in NPC1 mutant and Niemann–Picks disease." (PMID 36230953, 2022). "Likewise, mutations in the NPC1 (NPC intracellular cholesterol transporter 1) and SMPD1 (sphingomyelin phosphodiesterase 1) genes, which cause Niemann-Pick disease, have been shown to be risk genes for IPD." (PMID 36525454, 2022). "Based on the known roles of NPC1 in the Niemann–Pick disease, there are numerous mechanisms through which impaired growth and invasion may occur." (PMID 35884604, 2022). "Taken together our results show that Rab7 and its trimeric Mon1-Ccz1-C18orf8 (MCC) GEF control cellular cholesterol homeostasis through coordinated regulation of LDL trafficking and NPC1-dependent lysosomal cholesterol export, making it a potential therapeutic target in Niemann Pick disease." (PMID 33144569, 2020). "While NPC1 has not been explored in cancer, the literature on Niemann–Pick disease demonstrates the relevance of NPC1 in cholesterol and mitochondrial metabolism, which were evaluated next in the context of TNBC." (PMID 35884604, 2022). "In the NPC1 pathway, a considerable portion of LDL cholesterol is transported first to the TGN before arrival at the ER, and the TGN is depleted of cholesterol in Niemann–Pick disease." (PMID 30902833, 2019). "For example, the antagonistic interaction of Ebola virus (and/or related filoviruses) with the bat cell surface receptor, Niemann-Pick disease, type C1 (NPC1), has driven the rapid evolution of the receptor without affecting the transport of cholesterol, critical to the health of the host." (PMID 27711183, 2016).